IL1B (interleukin 1 beta)
Diseases named in the same sentence as IL1B in open-access papers (continued):
Sharing a sentence is not in itself a finding about the gene and the disease.
neuroblastoma (continued). "We found significant differences in the serum levels of IL-1β, IL-6, IL-12p40, IL-12p70, TNF-α, IFN-γ, IL-8 and MCP1 between patients with neuroblastoma and the control group." (PMID 40722593, 2025). "In neuroblastoma SH-SY5Y cells, previous studies observed that LPS treatment resulted in the enhanced synthesis of proinflammatory cytokines like TNF-α, IL-1β, and IL-6, while there was a decrease in anti-inflammatory cytokines like IL-10." (PMID 38671881, 2024). "Treatment of the AD SH-SY5Y (human neuroblastoma cells) cell model with DPEO resulted in decreased intracellular levels of Aβ, GSK-3β, P-Tau, IL-1β, TNF-α, IL-6, COX-2, OFR, and HFR, alongside reduced AchE and BchE activities and increased SOD activity." (PMID 39056736, 2024). "Currently, ELISA analysis indicated that propofol treatment suppressed inflammation in neuroblastoma cells exposed to MPP+ by decreasing the levels of TNF-α and IL-1β." (PMID 35350655, 2022). "Transfection of shTHRIL was performed in human neuroblastoma SH-SY5Y cells, followed by the detection of the levels of IL-6, IL-1β, and TNFα." (PMID 33675584, 2021). "Our results showed that Rgs10-/- macrophages produced higher levels of pro-inflammatory cytokines including TNF, IL-1β and IL-12p70 in response to LPS treatment and exerted higher cytotoxicity on dopaminergic MN9D neuroblastoma cells." (PMID 24278459, 2013). "We show here that exposure of a human neuroblastoma cell line (SK-N-MC cells) to TNF-α promotes ROS-mediated caspase-1 activation and IL-1β secretion." (PMID 23940760, 2013). "We also demonstrate that neuroblastoma cells are able to produce PGE2, and that incubation with arachidonic acid or IL-1β increases the production." (PMID 22276108, 2012). "Furthermore, it has been shown to exert neuroprotective effects in human neuroblastoma (SHSY5Y), with mitigation of anti-inflammatory markers such as IL-1β and TNF-α and decreased ROS levels." (PMID 40943313, 2025). "In line with that, in an in vivo study, sulforaphane was observed to reduce inducible nitric oxide synthase (iNOS), proinflammatory levels (IL-1β, IL-6), cyclooxygenase-2 (COX-2), and nuclear factor (NF)-κB p-p65 in mouse neuroblastoma N2a cells expressing APPswe." (PMID 39493676, 2024). "We next evaluated the effects of non-toxic doses of AM404 and acetaminophen on IL-1β-induced PGE2-release in human SK-N-SH neuroblastoma cells." (PMID 34867421, 2021). "Therefore, we investigated the effect of WNV infection on the expression of key pro-inflammatory cytokines such as IL-1β, -6, -8, -18 and TNF-α in human neuroblastoma cell line SK-N-SH at both mRNA and protein levels." (PMID 21034511, 2010). "DNA methylation status of CpG and non-CpG moieties in the 5′-flanking regions of the IL-1β and IL-6 genes has been studied by bisulphite treatment of genomic DNA purified from human neuroblastoma SK-N-BE cells, cultured for 24 h in control or 0.5 mM ALA supplemented medium." (PMID 28954414, 2017). "Microglial BV-2 cells, but not neuroblastoma SH-SY5Y cells, released the pro-inflammatory cytokines IL-1β and TNF-α." (PMID 34281258, 2021). "This neuroblastoma cell line is known to secrete TNF- α and IL-1β, regardless of differentiation." (PMID 34281258, 2021).
ZIKV infection (54 papers, 2017 to 2025). "Our current study sheds light on the possibility of using AP as an alternative agent for treating complications caused by ZIKV infection-induced IL-1β secretion." (PMID 36559293, 2022). "Here we initially showed that IL-1β levels in the sera of ZIKV-infected patients (n = 11) were higher than those in healthy individuals (n = 13), suggesting that ZIKV infection is associated with IL-1β secretion." (PMID 29317641, 2018). "Additionally, genes encoding cytokines and chemokines, including IL-1α, Il-1β, Cxcr4, and Cxcl10, were significantly upregulated in response to ZIKV infection, suggesting the presence of neuroinflammation." (PMID 39273400, 2024). "In response to ZIKV infection, interleukin-1β (IL-1β) was highly increased, suggesting that it may be the cause of the ZIKV-associated diseases." (PMID 36559293, 2022). "Hence, whether IL-1β and C3 expression in the brain is affected by ZIKV infection needs to be investigated to explore ZIKV-associated neurological diseases." (PMID 37191498, 2023). "We found that during acute infection, ZIKV infection induces robust expression of inflammatory genes, such as IL-6, TNFα, and IL-1β in the brain." (PMID 40688087, 2025). "Our studies show elevated IL1β and TNFα gene expression up to day 7, likely driven by ZIKV infection and apoptosis in brain tissue." (PMID 40688087, 2025). "Expression analysis of neuroinflammatory markers revealed that melatonin reduced IL-1β, TNFα, and NF-κB during ZIKV infection." (PMID 40821819, 2025). "MEL treatment reduced viral brain loads by 3–4 log units and modulated neuroinflammatory markers, notably reducing IL-1β, TNFα, and NF-κB during ZIKV infection, and modulating TNFα, IL-1β, and NF-κB during DENV-4 infection." (PMID 40821819, 2025). "ZIKV infection causes severe inflammation through NOD-, LRR-, and pyrin domain-containing protein 3 (NLRP3) inflammasome-mediated IL-1β production." (PMID 36831177, 2023). "Using human monocyte THP-1 cells, we confirmed that ZIKV infection promotes inflammatory cell death and increases IL-1β secretion." (PMID 37191498, 2023). "Taken together, our findings indicate that the induction of C3 and complement activation by ZIKV infection is mediated by the IL-1β signaling pathway." (PMID 37191498, 2023). "TNF-a presents the potential to cause neural tube defects, IFN-g is related to impaired placental development following Zika virus infection, and IL-1b can induce preterm labor." (PMID 37376620, 2023). "A study has reported that the levels of proinflammatory cytokines such as IL-1β, interferon-γ, and IL-8 are increased in patients with ZIKV infection." (PMID 38249297, 2023). "We demonstrated that ZIKV infection of the brain in this animal model augments IL-1β expression in infiltrating macrophages and elicits IL-1β-mediated inflammation, thereby leading to the destructive consequences of neuroinflammation." (PMID 37191498, 2023). "In summary, ZIKV infection of the brain induced the expression of proinflammatory cytokines, including IL-1β, IL-6, IFN-γ, and TNF-α, in Ifnar1−/− mice." (PMID 37191498, 2023). "Cells or mice deficient in NLRP3 exhibited a decreased secretion of IL-1β and increased type I IFN production following ZIKV infection, as well as increased host resistance to ZIKV-induced effects in vivo and in vitro." (PMID 36831177, 2023). "Taken together, our results suggest that ZIKV infection in the brain of this animal model augments IL-1β expression in infiltrating macrophages and elicits IL-1β-mediated inflammation, which can lead to the destructive consequences of neuroinflammation." (PMID 37191498, 2023). "Diacerein, an inhibitor of IL-1β production, and an IL-1R antagonist effectively reduced the ZIKV-mediated C3 induction in a dose-dependent manner, thereby suggesting the involvement of IL-1β in the induction of C3 gene expression by ZIKV infection." (PMID 37191498, 2023).
ZIKV infection (continued). "Our results suggest that ZIKV infection in the mouse brain can induce IL-1β-mediated inflammation and complement activation, thereby contributing to the development of neurological disorders." (PMID 37191498, 2023). "ZIKV infection induced the expression of proinflammatory cytokines, including interleukin-1β (IL-1β), IL-6, gamma interferon, and tumor necrosis factor alpha, in the brains of Ifnar1−/− mice." (PMID 37191498, 2023). "ELISA revealed that, compared to the mock infection, ZIKV infection significantly augmented IL-1β secretion over time." (PMID 37191498, 2023). "While vertical transmission during ZIKV infection contributes to adverse outcomes, we and others have shown that the maternal immune response, including elevated production of IL-1β, also plays a key role in pathogenesis." (PMID 37581940, 2023). "ZIKV infection upregulated C3 expression through IL-1β-mediated signaling, possibly disrupting the balance of the complement system, which can mediate myelin phagocytosis by macrophages." (PMID 37191498, 2023). "To validate the role of C/EBP-β in IL-1β-mediated induction of C3 expression by ZIKV infection in THP-1 cells, we infected cells with ZIKV at 5 MOI and analyzed the activation of P38, Erk1/2, and C/EBP-β using Western blotting." (PMID 37191498, 2023). "ZIKV infection can increase the transcription of proinflammatory cytokines such as IL-1β and IL-6 by activating the NF-κB signaling pathway." (PMID 38249297, 2023). "Using the same automated enzyme-linked immunosorbent assay workflow, IL-1β and CXCL10 were quantified after ZIKV infection through D11C (6 μg/mL)." (PMID 35862953, 2022). "Our data confirmed the enrichment of cell death pathways during ZIKV infection, as well as of IL-1β cytokine signaling pathways, also evidencing death by pyroptosis." (PMID 36142200, 2022). "Expression analysis via qRT-PCR showed that ZIKV infection induced significant upregulation of each of the cytokines analyzed, including Ifna6, Ifnb, Ifng, Il1b, Il6, and Tnfa." (PMID 35462541, 2022). "Results clearly showed that mock-infected cells showed very low positive basal level of intracellular IL-1β while ZIKV infection markedly increased the production of IL-1β in THP-1 macrophages." (PMID 36559293, 2022). "As expected, the immunoreactive band of IL-1β was detected in the culture supernatants of THP-1 macrophages with ZIKV infection, and AP at all concentrations effectively reduced the intensity of IL-1β-positive immunoreactive bands." (PMID 36559293, 2022). "The level of IL-1β in the supernatant of ZIKV-infected THP-1 macrophages was tested by Western blotting confirming that ZIKV infection can activate human macrophage response by secreting IL-1β into the extracellular environment." (PMID 36559293, 2022). "Previous studies have demonstrated that ZIKV infection activates inflammatory pathways and facilitates the secretion of pro-inflammatory cytokine interleukin-1β (IL-1β) in vitro and in vivo." (PMID 35972780, 2022). "Particularly, one study reported that patients or mice with ZIKV infection exhibited high levels of IL-1β in the serum." (PMID 36559293, 2022). "The levels of cytokines, including Il1b, Tnfa, and Il12, were all diminished in Peli1−/− macrophages following ZIKV infection." (PMID 32544190, 2020). "Elevated levels of placental type I IFNs and IL-1β were reported to promote fetal demise upon congenital ZIKV infection." (PMID 32544190, 2020). "ZIKV infection elicits pyroptosis in the brains of fatal microcephaly cases and increases IL-1β expression." (PMID 32611752, 2020). "Given that previous literature suggests a role of inflammasome during ZIKV infection, we also evaluated the secretion levels of IL-1β, a key cytokine of inflammasome activation." (PMID 33207682, 2020).
ZIKV infection (continued). "The IL-1β upregulation was observed in human brain microvascular endothelial cells after ZIKV infection, followed by decreased proinflammatory cytokine levels when IL-1 receptor antagonist was added to model." (PMID 32580374, 2020). "We show that ZIKV infection activates proinflammatory (IL-1β) cytokines as well as chemokines (CCL2, CCL5, GM-CSF, G-CSF, CXCL1, and CXCL12) in the endothelial cells." (PMID 31249527, 2019). "In this study, a novel mechanism by which ZIKV infection activates the NLRP3 inflammasome to facilitate IL-1β maturation is revealed." (PMID 29317641, 2018). "ZIKV infection was associated with concomitant secretion of inflammatory mediators linked with central nervous system inflammation such as IL-6, TNF-α, IL-1β, iNOS and NO." (PMID 30359409, 2018). "ZIKV infection is associated with IL-1β secretion in infected patients, and ZIKV activates IL-1β secretion in infected human PBMCs, macrophages, mice, and mice BMDCs, suggesting that ZIKV infection activates IL-1β secretion." (PMID 29317641, 2018). "Taken together, we demonstrate that ZIKV infection induces severe inflammatory responses in mice through Casp-1-mediated activation of IL-1β." (PMID 29317641, 2018). "In C57BL/6 WT mice, ZIKV infection activates IL-1β production and induces inflammatory responses, and Casp-1 is involved in such activations." (PMID 29317641, 2018). "Next, the effect of ZIKV infection on the activation of IL-1β was determined in A129 mice treated with Ac-YVAD-cmk." (PMID 29317641, 2018). "In addition to these cytokines, GM-CSF, IL-1B, IL-2, IL-6, IL-17, and IL-22 have been observed in the acute phase of Zika virus infection." (PMID 41417343, 2025). "In addition to the increase in IL-1β secretion, cell death was promoted by ZIKV infection in THP-1 cells, possibly due to pyroptosis." (PMID 37191498, 2023). "The increase in C3 levels by ZIKV infection is mediated by IL-1β signaling." (PMID 37191498, 2023). "Given the key role of NLRP3 inflammasome in innate immune responses by activating caspase-1 to promote IL-1β secretion and pyroptosis, we examined whether ZIKV infection stimulates IL-1β secretion through NLRP3 inflammasome activation in THP-1 cells." (PMID 37191498, 2023). "ZIKV infection of THP-1 cells induces IL-1β secretion and inflammatory cell death." (PMID 37191498, 2023). "Therefore, we demonstrated that ZIKV infection in THP-1 cells promotes C/EBP-β expression through IL-1β induction, eventually resulting in increased C3 levels." (PMID 37191498, 2023). "In addition, expression of the complement component C3, which is associated with neurodegenerative diseases and known to be upregulated by proinflammatory cytokines, was induced by ZIKV infection through the IL-1β-mediated pathway." (PMID 37191498, 2023). "Overall, our data suggest that ZIKV infection in the brains of Ifnar1−/− mice augments IL-1β expression in infiltrating macrophages and elicits IL-1β-mediated inflammation through macrophage activation, which can be associated with the destructive consequences of neuroinflammation." (PMID 37191498, 2023). "Since ZIKV infection has been reported to stimulate IL-1β production, in part through activation of NF-κB signaling, we thus tested whether AP can suppress ZIKV-induced activation of NF-κB." (PMID 36559293, 2022). "We noticed that even the lowest concentration of AP (1.56 μM) could effectively inhibit intracellular production of IL-1β in response to ZIKV infection." (PMID 36559293, 2022). "Since it has been reported that ZIKV infection can induce the immune cells to respond by secreting IL-1β into the extracellular environment leading to inflammation, we then tested the effect of AP on IL-1β secretion upon ZIKV infection." (PMID 36559293, 2022).
ZIKV infection (continued). "This statement can be supported by a previous study reporting that placental ZIKV infection induced IL-1β secretion, which provoked perinatal developmental abnormalities, and IL-1 receptor antagonist treatment alleviated ZIKV-induced placental dysfunction and perinatal injury." (PMID 36559293, 2022). "Additionally, qPCR assay confirmed the reduction of mRNA levels of Ifnb, Il1b, and Tnfa in Smaducin-6 treated hNS/PCs following ZIKV infection." (PMID 32544190, 2020). "ZIKV infection also caused infiltration of CD45 and IL-1β–positive cells in the placental labyrinth, which could be inhibited by FA treatments." (PMID 32392268, 2020). "In the same study, ZIKV infection was associated with concomitant secretion of inflammatory mediators linked to CNS inflammation and alterations in endothelial and microvascular permeability, such as IL-6, TNF-α, IL-1β, iNOS, and NO." (PMID 31620112, 2019). "We found that both of ZIKV infection and recombinant IL-1β treatment resulted in a significant decrease expression of AQP1 and AQP2 in primary murine renal epithelial cells thus inducing water re-absorption disorder, which indicated that inflammasome was involved in ZIKV-induced renal dysfunction." (PMID 31474993, 2019). "Thus we demonstrate that ZIKV infection triggers IL-1β secretion by activating the NLRP3 inflammasome." (PMID 29317641, 2018). "Finally, ZIKV infection in mice activates IL-1β secretion, leading to inflammatory responses in the mice brain, spleen, liver, and kidney." (PMID 29317641, 2018). "Notably, similar to what has been reported in ZIKV infection of microglial cells, IL1B was downregulated at 48 hpi." (PMID 29036922, 2017). "Importantly, ZIKV infection increased IL-1β and TNF-α expression levels and blockade of these cytokines decreased Ca2+ influx and neuronal cell death." (PMID 28878777, 2017). "We then investigated whether IL-1β expression in macrophages was mediated by direct ZIKV infection." (PMID 37191498, 2023). "However, whether IL-1β and C3 expression in the brain is affected by ZIKV infection remains to be investigated." (PMID 37191498, 2023). "Hence, agents that can inhibit the production or maturation of IL-1β in response to ZIKV infection may help reduce IL-1β–mediated diseases." (PMID 36559293, 2022). "In addition, ZIKV infection induces high levels of IL-17, IL-6 and IL-1β." (PMID 35215843, 2022). "Moreover, ZIKV-activated microglia may also facilitate astrocyte activation through the production of TNF-α and IL-1β, which were highly expressed in the brain following ZIKV infection." (PMID 32843067, 2020). "Indeed, ZIKV infection induced high levels of brain inflammatory cytokines, including IL-1β, which may facilitate the expression of IL-22 from γδ T cells." (PMID 32843067, 2020). "During ZIKV infection, MEL reduces expression of TNFα, MX1 and IFI44L but significantly increases expression of IL-1β and IFNβ." (PMID 40821819, 2025). "Inflammatory cytokines (e.g., IL-1β, IL-6, and TNF-α) induced following Zika virus infections in human macrophages also upregulate CH25H in type I IFNs in an independent manner." (PMID 37631994, 2023). "ZIKV infection of THP-1 cells induced pyroptosis, increased IL-1β release, and consequently increased C3 expression." (PMID 37191498, 2023). "On the basis that AP possesses strong anti-inflammatory activities in several different models, we thus explored the effects of this flavonoid on suppressing the release of IL-1β from TPA-activated THP-1 macrophages, in response to ZIKV infection." (PMID 36559293, 2022). "The results showed that acute ZIKV infection induces more intensive GDF3, NLRP3, IL-1β, and IL-18 expression in the context of pregnancy." (PMID 35632746, 2022). "Previous studies have demonstrated that ZIKV infection or the virus’ NS5 protein triggered intracellular production of ROS which further induced inflammasome activation, which is responsible for IL-1β production." (PMID 36559293, 2022).